SNX19 (sorting nexin 19)
Description:
Plays a role in intracellular vesicle trafficking and exocytosis. May play a role in maintaining insulin-containing dense core vesicles in pancreatic beta-cells and in preventing their degradation. May play a role in insulin secretion. Interacts with membranes containing phosphatidylinositol 3-phosphate (PtdIns(3P)) (By similarity).
Synonyms: KIAA0254; CHET8
Tractability: Antibody: UniProt places it where antibodies can reach, with high confidence. PROTAC: ubiquitination databases record sites on it; its protein half-life has been measured.
Gene: Protein-coding gene on chromosome 11 (130,866,250 to 130,916,479, reverse strand). Ensembl gene ENSG00000120451.
Subcellular location: Early endosome membrane; Cytoplasmic vesicle membrane
Subcellular location (Human Protein Atlas): Mitochondria
Gene Ontology:
Molecular function: protein binding; phosphatidylinositol binding; phosphatidylinositol-3-phosphate binding
Biological process: chondrocyte differentiation; dense core granule maturation; insulin secretion
Cellular component: cytoplasm; early endosome membrane; cytoplasmic vesicle membrane
Genetic constraint (gnomAD): Loss-of-function variants: 59 observed, 82.96 expected, observed/expected ratio (o/e) 0.71, 90% interval 0.58 to 0.88. The upper end of that interval is the gene's LOEUF score, 0.88, which puts it in group 3 of 6, group 1 being the genes least tolerant of losing a copy. Missense variants: 1,180 observed, 1,238.7 expected, observed/expected ratio (o/e) 0.95, 90% interval 0.91 to 1. Synonymous variants: 511 observed, 478.44 expected, observed/expected ratio (o/e) 1.07, 90% interval 0.99 to 1.15.
Homologues: Orthologues: chimpanzee SNX19 (98% identical), macaque SNX19 (93% identical), rabbit SNX19 (84% identical), pig SNX19 (82% identical), guinea pig SNX19 (82% identical), mouse Snx19 (82% identical), rat Snx19 (81% identical), zebrafish snx19b (45% identical), zebrafish snx19a (38% identical), dog SNX19 (33% identical), tropical clawed frog snx19 (26% identical). Paralogues in human: SNX13 (17% identical), SNX25 (16% identical), SNX14 (16% identical).
Diseases named in the same sentence as SNX19 in open-access papers:
SNX19 is named in the same sentence as 14 diseases in open-access papers, as found by Europe PMC text mining. Sharing a sentence is not in itself a finding about the gene and the disease. The quoted sentences say what the papers report.
schizophrenia (8 papers, 2018 to 2023). A major psychotic disorder characterized by abnormalities in the perception or expression of reality. "SNX19, a central regulator of cell trafficking and signal transduction, has been identified as one of the genes associated with diabetes and schizophrenia." (PMID 39132059, 2022). "We found that a few genes identified by MSG had been reported to influence schizophrenia risk via splicing (Note 1 Section 1C in S1 Appendix), including SNX19, AS3MT, and CYP2D6." (PMID 35771864, 2022). "SNX19, the RGS deprived PXA-RGS member, is regarded as a genetic risk factor for schizophrenia, where multiple SNX19 transcripts can be of etiological relevance for this complex disorder." (PMID 33931804, 2021). "SNX19 has also been associated with conditions that display GABAergic dysfunction, such as schizophrenia (which will be later discussed in section 4.2)." (PMID 33931804, 2021). "SNX19 role is still quite poorly explored; nevertheless, available data associates it as genetic risk factor for schizophrenia." (PMID 33931804, 2021). "For example, SNX19 was reported to be associated with schizophrenia by seven research papers." (PMID 35412455, 2022). "Similarly, investigation of another schizophrenia risk gene, SNX19, in post-mortem human brain identified a group of alternatively spliced isoforms missing the SNX19 C-terminal protein domain." (PMID 34409069, 2021).
diabetes (3 papers, 2014 to 2022). "To examine whether altered expression of some of the identified candidate genes in the islet mQTL/eQTL analyses affect β-cell function and thereby potentially the development of diabetes, we silenced the expression of three selected genes; Gpx7, Gstt1 and Snx19, in clonal β-cells." (PMID 25375650, 2014).
coronary disease (2 papers, 2008 to 2009). "Polymorphisms in the SNX19 gene have been proposed to be associated with coronary disease and the JAM3 gene has previously been proposed as a candidate gene for the JBS cardiac phenotype." (PMID 20003197, 2009). "This small region contains several genes of interest; for example, polymorphisms in SNX19 have been reported to be associated with coronary disease, while ADAMTS8 is involved in regulating angiogenesis." (PMID 19000322, 2008).
thyroid oncocytic adenomas (2 papers, 2022 to 2025). "A study in the literature reported that SNX19, along with 18 other genes, was significantly overexpressed in thyroid oncocytic adenomas compared to the control group." (PMID 40136427, 2025). "Although there is no report on the relationship between SNX19 and HCV infection or HCC, it has been reported that 18 genes, including SNX19, were significantly overexpressed in thyroid oncocytic adenomas compared with their expression in controls." (PMID 39132059, 2022).
acute myeloid leukemia (1 paper, 2025). Acute myeloid leukemia (AML) is a group of neoplasms arising from precursor cells committed to the myeloid cell-line differentiation. "This suggests that EPZ004777 may exert a regulatory effect on SNX19 expression, potentially contributing to the inhibition of cancer cell proliferation and survival in acute myeloid leukemia." (PMID 40136427, 2025).
Ataxia (1 paper, 2021). Ataxia refers to impaired coordination of voluntary muscle movement. "Whereas biallelic mutations in the SNX14 gene are known to cause autosomal recessive spinocerebellar ataxia 20 (SCAR20), a disorder characterized by cerebellar atrophy, ataxia, and severe intellectual disability, mutations in the SNX19 gene have not yet been shown to cause a Mendelian disorder." (PMID 34315878, 2021).
injury (1 paper, 2023). Damage inflicted on the body as the direct or indirect result of an external force, with or without disruption of structural continuity. "SNX19 had suggestive single-nucleotide polymorphism association with ammonia-induced acute lung injury and had pathophysiological roles that could be associated with acute lung injury in different ways." (PMID 37280583, 2023).
type 1 diabetes (1 paper, 2025). "The first identified SNX19 interactor is islet antigen 2, a major autoantigen in type 1 diabetes, which is involved in the regulation of insulin secretion by pancreatic β cells and dopamine release in PC12 cells." (PMID 40002894, 2025).
cancer (1 paper, 2025). A tumor composed of atypical neoplastic, often pleomorphic cells that invade other tissues. "Overall, these findings show the promise of EPZ004777 as a therapeutic agent, with TPBG, ZNF185, and SNX19 serving as focal points for further research to refine its application in cancer treatment." (PMID 40136427, 2025). "However, there is limited data in the literature regarding the relationship between SNX19 and cancer." (PMID 40136427, 2025).
psychiatric disorder (1 paper, 2023). A disorder characterized by behavioral and/or psychological abnormalities, often accompanied by physical symptoms. "We identified three male-specific genes (ARSA, IGF1R, and SNX19) and two female-specific genes (LEMD2 and PCP4) in psychiatric disorders." (PMID 37794117, 2023).
tumor (1 paper, 2025). "EPZ004777 downregulated tumor-associated genes such as TPBG, ZNF185, and SNX19, suggesting its ability to inhibit tumor progression." (PMID 40136427, 2025). "Additionally, the expression of tumor-associated genes such as CT45A3, TPBG, HOXA4, ZNF185, and SNX19 was significantly downregulated." (PMID 40136427, 2025).
SNX19 also shares sentences with these, for which no sentence is quoted: autism (1 paper); autosomal recessive spinocerebellar ataxia 20 (1); Cerebellar atrophy (1).